ETS1 (ETS proto-oncogene 1, transcription factor)
Diseases named in the same sentence as ETS1 in open-access papers (continued):
Sharing a sentence is not in itself a finding about the gene and the disease.
gastric cancer (continued). "MiRNA 129 has been reported to have great potential as a therapeutic agent in select tumors including bladder cancer, colorectal cancer, gastric cancer, and lung cancer, and may inhibits cancer cell proliferation, metastasis and invasion through targeting relevant genes such as ETS1, CDK6, PAK5." (PMID 27050373, 2016). "Since previous studies indicate the important roles of Ets1 in the invasion and metastasis of cancer cells, we further investigated the effects of miR-9 over-expression and target gene restoration on the migration and invasion of gastric cancer SGC-7901 and AGS cells." (PMID 23383271, 2013). "Importantly, the current study reported the inverse correlation between miR-9 levels and the expression of cyclin D1 and Ets1 in gastric cancer tissues, implying that cyclin D1 and Ets1 may be negatively regulated by miR-9." (PMID 23383271, 2013). "To detect the effects of ETS1 and EFNA4 on gastric cancer cells, we performed wound healing and Edu experiments." (PMID 41162582, 2025). "Follistatin-like 1 (FSTL1), miR-23b, ETS1, and TCF4 have all been reported to be prognostic biomarkers for gastric cancer patients, mainly involved in tumor progression and tumor immunity." (PMID 34980151, 2022). "The expression levels of ETS1, IGF2, FOXM1 and E-cadherin were detected by qRT-PCR in the collection of human gastric carcinoma specimens and adjacent normal tissues (cohort A)." (PMID 33407516, 2021). "For the treatment of gastric cancer, it is a potential application in combination therapies targeting miR-23b, E2F1, Notch2 receptor, and Ets1 in the future." (PMID 26041881, 2015). "In summary, we have demonstrated, for the first time, that miR-9 represses the expression of cyclin D1 and Ets1 through directly targeting their 3′-UTR, thus inhibiting the proliferation, invasion and metastasis of gastric cancer cells." (PMID 23383271, 2013). "Transfection of si-CCND1 and si-Ets1 resulted in decreased expression of cyclin D1, pRB, Ets1 and MMP-9 in gastric cancer cells, respectively, when compared to those transfected with scramble siRNA (si-Scb)." (PMID 23383271, 2013). "Furthermore, high expression of ETS1 and TCF4 indicated poor prognosis, suggesting that ETS1 and TCF4 are potential prognostic biomarkers for gastric cancer." (PMID 34686186, 2021). "Panc-Ets1 promotes tumorigenesis and aggressiveness of gastric cancer cells interacting with NONO and favoring ERG-positive transcriptional activity on ETS-1 gene." (PMID 32722129, 2020). "The recruitment of a multimolecular complex composed by pancEts-1/NONO/ERG on the Ets-1 gene drives ETS-1 expression and contributes to tumorigenesis and gastric cancer progression." (PMID 32722129, 2020). "Overall, these results demonstrate that lncRNA pancEts-1 exhibits oncogenic properties that drive the progression of gastric cancer via regulating the NONO/ERG/Ets-1 axis." (PMID 29773901, 2018). "Stable knockdown or ectopic expression of pancEts-1 attenuated and facilitated the binding of ERG to Ets-1 promoter in gastric cancer cell lines, which was rescued by transfection of NONO or sh-NONO #2, respectively." (PMID 29773901, 2018). "In our series of 81 gastric cancer cases, univariate analysis revealed that the levels of either pancEts-1 (P < 0.001), NONO (P = 0.003), ERG (P < 0.001), or Ets-1 (P < 0.001) were respectively associated with poor survival of patients." (PMID 29773901, 2018). "However, another study showed that only Ets-1 is required to regulate CIP2A expression in prostate and gastric carcinoma." (PMID 25537503, 2015). "Lower miR-9 expression and higher transcript levels of cyclin D1 and Ets1 were observed in gastric cancer cell lines than those in normal gastric epithelial GES-1 cells." (PMID 23383271, 2013).
gastric cancer (continued). "Western blot, RT-PCR and real-time quantitative RT-PCR demonstrated that over-expression of miR-9 resulted in decreased protein and transcriptional levels of cyclin D1 and Ets1 in gastric cancer cells than those transfected with negative control vector (mock)." (PMID 23383271, 2013). "According to stage classification, mRNA expressions of Notch2 receptor and Ets1 but not E2F1 were increased in stomach adenocarcinoma specimens from patients with gastric cancer advanced stages II–IV, compared with early stage I, whereas levels of miR-23b were decreased." (PMID 26041881, 2015). "The interaction between NONO and panc-Ets-1 promotes ERG transactivation on the Ets-1 promoter, thus supporting the aberrant growth of gastric cancer cells." (PMID 32722129, 2020). "In gastric cancer, the interaction of pancEts-1 with NONO and ERG promotes ERG transactivation and upregulation of ETS-1 expression, which contributes to aberrant proliferation and invasiveness of gastric cancer cells." (PMID 32722129, 2020). "In this study, we demonstrate that ERG serves as a crucial transcriptional regulator that promotes the expression of Ets-1, while NONO functions as a coactivator of ERG in gastric cancer." (PMID 29773901, 2018). "In gastric cancer tissues, pancEts-1, NONO, and ERG were upregulated and significantly correlated with Ets-1 levels." (PMID 29773901, 2018).
colorectal cancer (34 papers, 2004 to 2026). A primary or metastatic malignant neoplasm that affects the colon or rectum. "ETS-1 plays a significant regulatory role in colorectal cancer, where its high expression is strongly associated with increased malignancy, lymph node metastasis, and distant metastasis." (PMID 40181983, 2025). "Fentanyl has decreased colony establishment and suppressed cell migration and invasion in colorectal cancer cells, whereas Ets-1 up-regulation has suppressed fentanyl-associated influences through down-regulation of BANCR (Li A.-x." (PMID 34409032, 2021). "In colorectal cancer, however, expression of Ets-1 protein was found to be significantly associated with lymph node status, depth of invasion and lymphatic invasion." (PMID 15365563, 2004). "Conversely, another study in colorectal cancer showed that high H3K27cr at the promoter of ETS1 gene led to an increase in its expression and promoted metastasis." (PMID 40810390, 2025). "The H3K27cr mark has been previously reported to activate the transcription of pro-tumorigenic ETS1 in colorectal cancer." (PMID 40810390, 2025). "MiR-532-3p can inhibit the progression of colorectal cancer by regulating ETS1-related signalling pathways." (PMID 35592424, 2022). "Ets1 is well characterized as a proto-oncogene transcription factor due to its high expression related to poor prognosis in cancers, including colorectal cancer, and the transcriptional regulation of genes related to cell migration, invasion, and replication." (PMID 36305724, 2022). "We also performed an expression analysis of ETS1 and TGM2 with TCGA colorectal cancer datasets and verified that the expression level of ETS1 positively correlated with that of TGM2." (PMID 31570702, 2019). "The data in the present study indicated that the total expression percentage of integrin αvβ6 and Ets-1 in colorectal cancer was 36.07% and 57.59% respectively." (PMID 25264483, 2014). "The correlation analysis confirmed the expression of αvβ6 and Ets-1 were positively correlated in colorectal cancer." (PMID 25264483, 2014). "A transcription regulatory complex (TRC) that includes Ets1, Ets2, PEA3 and β-catenin/T-cell factors regulates osteopontin (OPN) that is implicated in colorectal cancer (CRC) dissemination." (PMID 21343932, 2011). "ETS-1’s interaction with immune cells and matrix components in the tumor microenvironment affects local inflammation and immune evasion, further contributing to colorectal cancer progression." (PMID 40181983, 2025). "Thus, ETS-1 serves as both a key regulator in colorectal cancer biology and a potential therapeutic target." (PMID 40181983, 2025). "Similarly, a series of experimental analyses in colorectal cancer cell lines have confirmed the existence of the circFOXP1/miR-338-3p/ETS1 axis." (PMID 39606233, 2024). "Ets1, Sp1 and Src all regulate cell progression in colorectal cancer, and additionally, both Ets1 and Src are highly expressed in colorectal cancer, implying that there may be reciprocal links between Ets1, Sp1 and Src in the development of colorectal cancer." (PMID 36305724, 2022). "The ETS1 has been shown to be a driving factor for the progression of majority cancers and its down-regulation inhibits the progression of colorectal cancer." (PMID 35992347, 2022). "Ets1 and Sp1 regulate cell progression in colorectal cancer." (PMID 36305724, 2022). "However, further research is needed to confirm the findings and to establish the relationship between the αvβ6 and Ets-1 as a significant prognositic indicator for colorectal cancer." (PMID 25264483, 2014). "Moreover, miR-221 suppresses colorectal cancer metastasis and invasion by down-regulating c-kit Stat5A and ETS1." (PMID 24721839, 2014).
colorectal cancer (continued). "Hence, the combination of αvβ6 and Ets-1 can be used as a prognostic marker in colorectal cancer, especially for the early stage." (PMID 25264483, 2014). "Based on these data, we confirmed that the concomitant expression of αvβ6 and Ets-1 in colorectal cancer cells could be used as an independent predictor to determine early relapse, metastases and prognosis in CRC patients." (PMID 25264483, 2014). "To Date, based on this study results and other previous conclusions, we think that co-expression of αvβ6 and Ets-1 could serve as a significant prognositic indicator for colorectal cancer, and their interaction might play an important role in cancer progression." (PMID 25264483, 2014). "Another study in colorectal cancer cells has revealed the effects of Fentanyl on induction of BANCR over-expression and Ets-1 under-expression." (PMID 34409032, 2021). "Furthermore, ETS-1 can induce epithelial-mesenchymal transition (EMT), increasing the invasive and migratory capabilities of colorectal cancer cells, thereby facilitating metastasis." (PMID 40181983, 2025). "Besides, ETS1 could regulate cell viability via interfering glycolysis in pancreatic cancer; increased expression of ETS2 promotes drug resistance in colorectal cancer." (PMID 33585247, 2020).
glioma (33 papers, 2009 to 2025). A benign or malignant brain and spinal cord tumor that arises from glial cells (astrocytes, oligodendrocytes, ependymal cells). "We additionally analyzed the expression of a panel genes (Angpt2, Sox4, Vegfa, Kdr, Itga1, Mcam, Notch4 and Ets1) associated with vascular abnormality in ECs using RNA extracted from total glioma tumor tissues from control and treated mice." (PMID 34867089, 2021). "On the other hand, ETS Proto-Oncogene 1 (ETS1) is expressed in different cancer subtypes and has been associated with the degree of glioma cell invasiveness." (PMID 33322092, 2020). "This suggested that the p52-driven augmentation of ETS1 genomic binding may increase the co-association and cooperativity between ETS1 and different transcriptional co-activators that are overexpressed in gliomas." (PMID 37087499, 2023). "Interestingly, elevated ETS1 expression was also observed in vasculature of the normal isocitrate dehydrogenase (IDH-WT) lower-grade gliomas (LGGs) compared with vasculature of IDH-mutated LGGs in our previous study." (PMID 34228647, 2021). "Finally, seen from the results of wound healing and transwell assays, we knew that the hampered migration and invasion of glioma cells with ETS1 deficiency was recovered after further overexpressing SNHG10, inhibiting miR-532-3p or up-regulating FBXL19." (PMID 33298070, 2020). "The evidence provided by this study supports the stance that the lncRNA PAXIP1-AS1/ETS1/KIF14 axis is implicated in the aggression potential of glioma and may be targeted for the development of therapies." (PMID 31823805, 2019). "Seeking to understand the underlying mechanism, we considered prior studies identifying HIF1A as a direct client of HSP9025, and noting that HIF1A was reported to bind the ETS1 promoter in glioma cells." (PMID 40777467, 2025). "Collectively, these findings demonstrate that p52 activation drives a glioma-specific alteration in the genomic landscape of ETS1 that is enriched in accessible chromatin." (PMID 37087499, 2023). "The overexpression of ETS1 alters its genomic binding dynamics and transcriptional activities, which in turn impacts glioma invasion and survival." (PMID 37087499, 2023). "We conclude that p52-induced ETS1 overexpression in glioma cells remodels the genome-wide regulatory network of p52 and ETS1 to transcriptionally drive cancer progression." (PMID 37087499, 2023). "Overexpression of PAXIP1-AS1 advances glioma development by recruiting the transcription factor ETS1 to increase KIF14 expression." (PMID 37582104, 2023). "Altogether, these results highlight the functional importance and clinical relevance of p52-driven ETS1 genomic binding in glioma-specific progression." (PMID 37087499, 2023). "Taken together, these findings demonstrate the role of p52-induced ETS1 genomic binding in the transcriptional activation of distinct target genes that are critical for glioma progression." (PMID 37087499, 2023). "We further demonstrate that ETS1 functionally cooperates with p52 to promote glioma invasion and cell proliferation." (PMID 37087499, 2023). "p52-induced ETS1 overexpression in glioma cells remodels the genome-wide regulatory network of p52 and ETS1 to transcriptionally drive cancer progression." (PMID 37087499, 2023). "Unexpectedly, we found that nearly 60% of all p52 binding sites were lost following ETS1 KD in TWEAK-activated glioma cells." (PMID 37087499, 2023). "Having identified IRE1α as a target gene of p52 and ETS1 cooperativity, we proceeded to validate its functional roles in glioma progression by performing short hairpin RNA (shRNA)-mediated KD of the gene in U-87 MG and U-251 MG cell lines." (PMID 37087499, 2023). "To functionally validate the role of p52-activated ETS1 in glioma progression, we targeted NFKB2 and ETS1 expression in U-87 MG and U-251 MG cells using CRISPR-Cas9 gene editing tools and verified their downregulation through western blotting." (PMID 37087499, 2023).
glioma (continued). "We also observed that TWEAK-regulated ETS1 DNA binding was highly enriched at over-accessible chromatin regions in glioma patients, and ETS1 activation consequently supports glioma invasion and tumour proliferation." (PMID 37087499, 2023). "Our data further provides functional evidence for the relevance of p52:ETS1 cooperativity in the transcriptional regulation of glioma-promoting genes." (PMID 37087499, 2023). "Altogether, our data indicate the crucial role of NF-κB/p52 activation in enhancing the genomic binding landscape of ETS1 to drive glioma progression." (PMID 37087499, 2023). "We further investigated the direct cooperative role of TWEAK-driven p52:ETS1 and demonstrated its capacity to regulate and drive glioma progression." (PMID 37087499, 2023). "Among the transcription factors regulated by ERK1/2 and involved in cell proliferation, CREB and ETS1 are known to modulate malignant features of glioma cells controlling transcription of GBM genes." (PMID 35982038, 2022). "LncRNA PAXIP1-AS1 was identified to boost migration and angiogenesis of glioma by upregulating ETS1-midiated KIF14 expression." (PMID 35440045, 2022). "Through conducting caspase 3/8/9 activity detection and TUNEL assay, we certified the facilitative effect of ETS1 knockdown on glioma cell apoptosis, while such impact was then rescued by SNHG10 up-regulation, miR-532-3p repression or FBXL19 overexpression." (PMID 33298070, 2020). "Such phenomenon was also certified by our present work, and we further proved that ETS1 exerted its promotion on glioma development by targeting SNHG10/miR-532-3p/FBXL19 signaling." (PMID 33298070, 2020). "In our previous study concerning BRAFV600E-positive high-grade glioma, ETS1 was the only ETS factor affected by BRAF inhibition." (PMID 33143299, 2020). "SNHG10 was transcriptionally activated by ETS1 and played an oncogenic role in glioma by sponging miR-532-3p and up-regulating FBXL19." (PMID 33298070, 2020). "Herein, we examined the expression and functional relevance of lncRNA PAXIP1-AS1 in glioma, which was involved with the ETS1/KIF14 axis." (PMID 31823805, 2019). "We note that overexpression of lncRNA PAXIP1-AS1 advances the development of glioma by recruiting the transcription factor ETS1 to increase KIF14 expression." (PMID 31823805, 2019). "Here, we have demonstrated that lncRNA PAXIP1-AS1 promoted glioma cell migration, invasion and angiogenesis by recruiting transcription factor ETS1 to upregulate KIF14 expression." (PMID 31823805, 2019). "Strikingly, BRAF-inhibition also blocked activating phosphorylation of ETS1 selectively in BRAFV600E-mutant glioma cells." (PMID 31391125, 2019). "We analyzed the expression of the major ETS-factors ETS1, GABPA, and GABPB with its splice variants, ETV1, ETV4 and ETV5 all of which were widely expressed across our glioma cell panel." (PMID 31391125, 2019). "Next, overexpression vectors and shRNAs were delivered to alter the expression of lncRNA PAXIP1-AS1, KIF14, and ETS1 to analyze their effects on glioma progression in vivo and in vitro." (PMID 31823805, 2019). "Expression of ETS-1 has also been shown to decrease adhesion in endothelial, HeLa and U251 glioma cells." (PMID 25421630, 2015). "Taken together, these observations demonstrate that TWEAK-induced p52 activation promotes glioma progression through enhanced ETS1 expression and remodelling of its genomic landscape, which is highly enriched at the over-accessible chromatin of glioma patients." (PMID 37087499, 2023). "To investigate the role of NF-κB/p52 in regulating the genomic occupancy of ETS1 in gliomas, we performed chromatin immunoprecipitation (ChIP) sequencing (ChIP-seq) using p52 and ETS1 antibodies in the glioma cell line, U-87 MG, with and without TWEAK treatment." (PMID 37087499, 2023). "This impacts the genomic and transcriptional landscape of ETS1 in a glioma-specific manner." (PMID 37087499, 2023).